IL1B (interleukin 1 beta)
Diseases named in the same sentence as IL1B in open-access papers (continued):
Sharing a sentence is not in itself a finding about the gene and the disease.
renal fibrosis (continued). "Results from Western blot also showed a reduction in the expression of renal fibrosis-related proteins (αSMA, Fn-1, Col3a1) and inflammatory factors (IL-1β, IL-6, TGF-β) in the kidney of acetate-treatment group." (PMID 36922584, 2023). "The consequently release of IL-1β and IL-18 activates macrophages in renal interstitium and aggravates tubular injury and renal fibrosis." (PMID 36732854, 2023). "Promoting SIRT1 expression can inhibit pyroptosis of renal tubular epithelial cells, reduce the release of IL-18 and IL-1β, and alleviate the progression of renal fibrosis in children with CHn." (PMID 37534327, 2023). "Caspase-11 was found to directly interact with caspase-1 in TECs, leading to maturation of IL-1β and renal fibrosis in unilateral ureteral obstruction mice." (PMID 37554279, 2023). "Previous researches have confirmed ALPK1 promotes renal fibrosis in mice by promoting the production of pro-inflammatory cytokines IL-1β, IL-8 and TNF-α." (PMID 36732854, 2023). "Alpha‐kinase 1 (ALPK1) is a master regulator in inflammation and has been proved to promote renal fibrosis by promoting the production of IL-1β in diabetic nephropathy (DN) mice." (PMID 36732854, 2023). "Compared with the sham group, the 5/6 Nx ApoE–/– mice exhibited a significant increase in the macrophage infiltration of the kidneys (nephritis), upregulation of IL-1β, generation of reactive oxygen species, reduced creatinine clearance, and renal fibrosis." (PMID 36552668, 2022). "Macrophage infiltration and interleukin 1β (IL-1β) upregulation are involved in inflammation-mediated renal fibrosis and CKD." (PMID 36552668, 2022). "The activation of the NLRP3 inflammasome promotes the activation of inflammatory caspases (caspase-1)-dependent pro-inflammatory hormones IL-1β and IL-18, which, in turn, promotes renal fibrosis." (PMID 36421424, 2022). "We observed attenuated TIR8 expression in renal tubular epithelial cells from animal models of UUO-induced renal fibrosis due to high levels of IL-1β and activated NF-κB (p-p65)." (PMID 33945104, 2021). "The present study highlights the importance of the IL-1β/MyD88-induced inflammation signaling in the development of hepatic and renal fibrosis." (PMID 34764877, 2021). "Expression of Fibronectin-1 in the kidney in the DN mice was significantly elevated, and the inflammatory factor IL-1β increased, thus suggesting an increase in renal fibrosis and inflammation in the DN mice model." (PMID 34221188, 2021). "A recent study has confirmed that the IL-1β/c-Myc pathway plays a vital role in renal fibrosis by regulating cell proliferation and differentiation." (PMID 34211565, 2021). "The results showed that AMSCs decreased Scr, M1 macrophages, M1/M2 macrophages, TNF-α, IL-6, IL-1β, and renal fibrosis and increased IL-10 and the number of M2 macrophages." (PMID 34112221, 2021). "Further studies demonstrated that TCSG from Baishouwu suppressed the development of hepatic and renal fibrosis through inhibiting MyD88 signal transduction activated by IL-1β and subsequent p38 MAPK and NF-κB p65 downstream signaling." (PMID 34764877, 2021). "The degree of renal fibrosis, assessed through expression of Fibronectin-1, and the expression of proinflammatory IL-1β were greater, and the expression of glucose transporter GLUT4 was lower in DN compared to control mice." (PMID 34221188, 2021). "At the same time, expression of inflammatory cytokines (Il1b, Csf2, Tnfa, and Cxcl10), renal fibrosis, and profibrotic genes (Col1a1, Col3a1, Fn1, and Vim) was lower in the FA-treated Casp9 HZ mice." (PMID 34739325, 2021). "Inflammatory cytokines, such as tumor necrosis factor-α (TNF-α), interleukin-1β (IL-1β), and IL-6, can directly mediate renal fibrosis through inflammatory infiltration, fibroblast activation and synthesis and degradation of ECM." (PMID 32372953, 2020).
renal fibrosis (continued). "The typical NLRP3/ASC/caspase-1/IL-1β/IL-18 axis promotes the pathophysiology of various kidney diseases by mediating inflammation, and this is likely a critical priming mechanism for renal fibrosis." (PMID 32039201, 2019). "On the other hand, TGF-β suppresses the synthesis of proinflammatory molecules, such as IL-2, alleviates renal fibrosis, and prevents the IL-1β-dependent proliferation of activated T cells." (PMID 30881587, 2019). "Here we found that deletion of RIPK3 or MLKL alleviated the NLRP3 inflammasome activation and IL-1β release in kidney after IRI corresponding with the reduction of renal fibrosis." (PMID 30158627, 2018). "In the early stages of UUO, the pro-inflammatory macrophage (M1) is the predominant macrophage phenotype, directly inducing renal fibrosis by releasing pathogenic mediators such as TNF-α, IL-1β, CCL2 and reactive oxygen species (ROS)." (PMID 28416741, 2017). "Zhang and colleagues first noted that CHOP−/− mice were protected from UUO-induced renal fibrosis, wherein loss of CHOP decreased UUO-induced apoptosis of tubular cells and the Hmgb1/TLR4/NFκB/IL-1β signaling." (PMID 29230213, 2017). "Furthermore, genetic and pharmacologic inhibition of ACSS2 both suppressed H3K9cr-mediated IL-1β expression, which thereby alleviated IL-1β-dependent macrophage activation and tubular cell senescence to delay renal fibrosis." (PMID 40375990, 2025). "Notably, blockade of IL-1 signalling with anakinra in such models significantly reduces blood pressure and renal fibrosis, further substantiating the role of IL-1β as a mediator of hypertensive renal injury." (PMID 40832143, 2025). "IL-1β was an important link between inflammation and renal fibrosis." (PMID 40460381, 2025). "It is possible that crotonylation levels of other residue, not only H3K9, might be regulated by ACSS2 and could possibly play roles in regulating IL-1b-mediated renal fibrosis." (PMID 38615014, 2024). "Furthermore, genetic and pharmacologic inhibition of ACSS2 both suppress H3K9cr-mediated IL-1β expression, which thereby alleviate IL-1β-dependent macrophage activation and tubular cell senescence to delay renal fibrosis." (PMID 38615014, 2024). "Furthermore, pharmacologic inhibition of ACSS2 can suppress H3K9cr-mediated IL-1β expression, which thereby alleviate IL-1β-dependent macrophage activation and tubular cell senescence to delay renal fibrosis." (PMID 39606030, 2024). "In vivo experiments indicated that XHYTF significantly reduced blood uric acid and creatinine levels, alleviated inflammatory cell infiltration in kidney tissues, reduced the levels of serum inflammatory factors such as TNF-α and IL1β, and ameliorated renal fibrosis in rats with UAN." (PMID 36865745, 2023). "IL-1β is a significant effector molecule downstream of the pyroptotic pathway and is involved in damage to the kidney, making it a possible therapeutic target for renal fibrosis." (PMID 37500614, 2023). "Notably, activated NLRP3 inflammasome contributed to the generation of pro-fibrotic factors, and the secretion of IL-1β/18 was an initial and vital occurrence of inflammatory responses in renal fibrosis." (PMID 37500614, 2023). "IL-1b is a pro-inflammatory cytokine and has been described as a marker of renal fibrosis." (PMID 38132237, 2023). "Western blot analysis showed increased expressions of ALPK1, phospho-NF-κB P65, GSDMD-NT, and IL-1β in renal tissues of DN mice and HK-2 cells, accompanied with increased renal fibrosis-related proteins (FN, α-SMA) and macrophages infiltration in interstitial areas." (PMID 36732854, 2023). "In addition, immunological effects of VD and VD analogs have been reported in mouse models of renal fibrosis and obstructive nephropathy, such as a reduction of IL-6 and IL-1β in the kidney and reduced T cell and macrophage infiltration." (PMID 36505422, 2022).
renal fibrosis (continued). "Hence, it is possible to control or reverse the occurrence of renal fibrosis by inhibiting the activation of inflammasomes or the excessive release of IL‐1β and the later amplification of inflammatory signals." (PMID 35560773, 2022). "Previous studies have shown that high glucose level significantly induces the expression of pyroptosis markers, including NLRP3, caspase-1, pro-caspase-1, IL-1β, and pro-IL-1β, in GMCs, whereas inhibiting NLRP3 with MCC950 suppresses NLRP3/caspase-1/IL-1β activation and decreases renal fibrosis." (PMID 36204129, 2022). "IL-1β contributes to renal damage; thus, its inhibition might offer a crucial way of preventing renal fibrosis." (PMID 36552668, 2022). "In addition, although we did not explore fibrosis-related proteins, the findings of Masson’s trichrome staining were consistent with some studies reporting a synergistic role of IL-1β in renal fibrosis." (PMID 36552668, 2022). "As CKD fibrosis progresses, senescent cells express and secrete pro-fibrotic factors (TGF-β, CTGF, and so forth) and pro-inflammatory factors (IL-1β, IL-6, TNF-α, and so forth), which are senescence-associated secretory phenotype factors, thereby accelerating renal fibrosis." (PMID 35227255, 2022). "In renal fibrosis, the loss of Chop gene represses Hmgb1/TLR4 signal pathway, leading to repressed NF-κB transcriptional activity along with suppressed IL-1β production, and reduced TGF-β1 production and PI3K/Akt activity to attenuate the development of fibrosis." (PMID 36357371, 2022). "Furthermore, Epithelial-mesenchymal transition (EMT) and Endothelial-mesenchymal transition (EndMT) caused by the higher levels of IL-6, IL-1β and TGF-β are the key mesenchymal inducers that play important roles in the renal fibrosis." (PMID 34054555, 2021). "A recent study reported that the use of a c-Myc inhibitor, 10058-F4, significantly attenuated renal fibrosis in vivo, and in vitro experiments confirmed that c-Myc inhibitors and siRNA silencing of c-Myc blocked IL-1β-induced fibroblast proliferation and activation." (PMID 34211565, 2021). "Taken together, these data indicate that the role of ASC in renal fibrosis is specific for IL-1β and IL-18, which are known to be processed by the inflammasome, though our evidence does not fully support the conclusion that this effect is inflammasome-dependent." (PMID 30057487, 2018). "SalB also reduces the expressions of inflammatory factors, such as interleukins (IL-1β, IL-6, and IL-8), alleviates apoptosis of vascular cells to improve heart function, reduces liver and renal fibrosis via down-regulating transforming growth factor β1 (TGF-β1) and depressing MMP-2 activity." (PMID 27893819, 2016). "In renal fibrosis, activation of the inflammasome and subsequent release of IL-1β, along with TNF-α and IFN-λ, contributes to the epithelial mesenchymal transition, a critical step in disease development that may have implications for PF." (PMID 21660282, 2011). "Furthermore, through the NLRP3/caspase-1/IL-1β pathway, IL-22 can reverse the overexpression of fibronectin, collagen IV, and extracellular matrix in mouse renal glomerular mesangial cells, thereby ameliorating renal fibrosis and proteinuria excretion in DN." (PMID 36776877, 2023). "PHLDA1 promotes IL-1β expression and the knockout of PHLDA1 suppressed NF-κB signaling and renal fibrosis." (PMID 41727481, 2026). "Similar phenomena are observed in renal fibrosis, where renal tubular epithelial cells transition into fibroblast-like cells under the stimulation of inflammatory factors (e.g., TGF-β, IL-1β)." (PMID 40423444, 2025). "This assembly promotes the release of inflammatory cytokines, such as IL-1β and IL-18, which in turn trigger the production of pro-fibrotic factors like TGF-β, fostering renal fibrosis." (PMID 39104818, 2024).
renal fibrosis (continued). "A subsequent study showed that HK-2 cells exposed to IL-1β strongly expressed TXNIP, NADPH oxidase 4 (Nox4), and ROS, indicating that inhibition of NLRP3 inflammasome activation suppresses renal fibrosis." (PMID 37500614, 2023). "Mitochondrial dysfunction activates inflammation through the mtDNA-cGAS-STING-NF-κB pathway in renal fibrosis, with higher levels of the proinflammatory cytokines IL-6, TNF-α and IL-1β." (PMID 36959860, 2023). "AMCZ markedly lowered the elevated levels of p-JNK, FN, Col-IV, α-SMA, IL-1β, and TNF-α in CKD rats, suggesting AMCZ attenuated renal fibrosis and inflammation through the modulation of SIRT1/JNK signaling pathway." (PMID 37089928, 2023). "Q-PCR indicated a significant reduction in the expression of renal fibrosis-related genes (fn-1, αSMA, Col1a1, Col3a1, Ctgf, fsp1, KIM) and inflammatory cytokines (Tgfα, Tgfβ, Il-1b, Il-4, Il-6, CD44, CD68) in the kidney of the acetate-treatment group." (PMID 36922584, 2023). "In the UUO-induced renal fibrosis model used in this study, autophagy induction protected fibrosis through the regulation of the expression of TGF-β1 and IL-1β." (PMID 35164031, 2022). "Studies have found that in the Uox-knock-out-induced HUA and nephropathy rat line, the PI3K inhibitor 3-MA alleviates kidney injury accompanied by renal fibrosis, macrophage infiltration, and expression of NLRP3 and IL-1β in injured kidneys." (PMID 36438835, 2022). "The results of the Western blot analysis showed increased expressions of inflammatory-related transcription factor (p-STAT3), inflammatory cytokines (IL-1β, TNF-α), NGAL, and fibrosis-related markers (α-SMA, fibronectin) in UUO-induced renal fibrosis." (PMID 36232665, 2022). "The results show that SQYSF can effectively reduce renal fibrosis in CKD mice, significantly reduce the expression of inflammatory factors TNF-α, IL-1β and IL-6, and can significantly change the composition of the mouse intestinal flora." (PMID 35184655, 2022). "Kaempferol showed the potential to improve histological changes and renal fibrosis while reducing the expression levels of TGF-β1, CTGF, fibronectin, collagen IV, IL-1β, RhoA, ROCK2, and P-MYPT1 in DKD renal tissue." (PMID 36466094, 2022). "Inhibition of autophagy with the PI3K inhibitor 3-MA abrogated the development of kidney damage and attenuated renal fibrosis, macrophage infiltration, and expression of NLRP3 and IL-1β in injured kidneys." (PMID 33648977, 2021). "We found that expression of the fibrotic protein α-SMA and inflammatory factor IL-1β was markedly reduced in the LN mouse model after treatment with CTX, which delayed the progression of renal fibrosis and inflammation." (PMID 34820026, 2021). "Candidate genes expression involved in renal fibrosis (TGF-β1, collagen type I and III) and inflammation (TNFα, IL-1β, IL-6 and MCP-1) were also measured by real-time qPCR." (PMID 33396267, 2020). "We found that treatment with BMSC-EVs reverse UUO-induced increase of inflammatory cytokines TNF-α, IL-6, and IL-1β and macrophage infiltration, indicating that EVs effectively protect against UUO-induced renal fibrosis by inhibiting the inflammatory response." (PMID 32586368, 2020). "Of note, other than stimulating TGF-β1 secretion, there is also evidence indicating that IL-1β can activate PI3K/Akt signaling, thereby enhancing renal fibrosis." (PMID 32076626, 2020). "Our UUO mouse model showed that a single injection of Nec-1 (inhibitor of RIPK1) ameliorated kidney injury, release of proinflammatory cytokines (IL-1β and TNF-α) and a chemokine (MCP-1), and renal fibrosis." (PMID 33390935, 2020). "IL-1β can also regulate the proliferation of mesangial cells, the production of ECM, and renal fibrosis." (PMID 31119177, 2019). "Further, our data showed the expressions of pro-inflammatory cytokines (mcp-1, IL-1β and TNF-α) and the renal fibrosis biomarkers fibronectin (Fn) and collagen IV (Col.IV) were significantly higher in H-MCs than those in L-MCs by qRT-PCR." (PMID 28151474, 2017).
renal fibrosis (continued). "Extracellular Hmgb1 thus bound to TLR4, and by which, it activated MyD88-NFκB pathway to enhance IL-1β expression, which in turn promoted TGF-β/Smad2/3 and Pi3k/Akt signaling to exacerbate renal fibrosis." (PMID 26247732, 2015). "It was further noted that reduced IL-1β production also inhibited UUO-induced PI3K/AKT signaling, and both of which ultimately protected mice from UUO-induced renal fibrosis." (PMID 26247732, 2015). "We demonstrated that TFNAs@PLT could reduce inflammation-mediated pyroptosis and apoptosis via Caspase-3/GSDME and NLRP3-mediated Caspase-1/IL-1β pathways in AKI, while also alleviating renal fibrosis through NLRP3/Caspase-1 and TNF-α/NF-κB pathways in CKD." (PMID 41355960, 2026). "NLRP3 is associated with renal fibrosis after UUO, whereas IL-1β, IL-18, and caspase-1 are not necessary for these pathways." (PMID 37685978, 2023). "SQYSF significantly reduced the degree of renal fibrosis in CKD mice, and remarkably down-regulated the expressions of toll-like receptor 5 (TLR5), nuclear factor-kappaB (NF-κb), p65, tumor necrosis factor (TNF)-α, interleukin (IL)-1β and IL-6." (PMID 35184655, 2022). "Also, the levels of damage markers in renal fibrosis, including ED-1 α-SMA, IL-6, IL-1β, TNF-α, TGF-β, NF-κB mRNA, CCL-2, CCL-5, collagen I, FN, collagen IV, and PCNA are decreased." (PMID 36268508, 2022). "Accumulating evidence also demonstrated that the nephroprotective effects of quercetin are related to inhibiting renal tubular epithelial-mesenchymal transition and renal fibrosis and reducing the production of cytokines in DN, including IL-6, TNF-α, and IL-1β." (PMID 34349833, 2021). "According to our in vitro findings, upregulated TGF-β1 levels induced by IL-1β in kidneys following UUO might play central roles in initiation and progression of renal fibrosis." (PMID 33945104, 2021). "Thus, the IL-1β downstream TGF-β1/Smad2/3 signaling was also inhibited, eventually ameliorating renal fibrosis." (PMID 29230213, 2017). "We demonstrated evidence that loss of Chop represses Hmgb1/TLR4 signaling following UUO induction, leading to repressed NFκB transcriptional activity along with suppressed IL-1β production, which then reduces TGF-β1 production and Pi3K/Akt activity to attenuate the development of renal fibrosis." (PMID 26247732, 2015). "Fibrosis reduction: MSCs decrease the levels of profibrotic factors such as IL-6, IL-1β, TNF-α, TGF-β, α-SMA, collagen I, and collagen IV while increasing the levels of antifibrotic factors such as FGFs, HGF, and VEGF, all of which inhibits EMT and reduces renal fibrosis." (PMID 40093796, 2025). "Similar to the findings in renal fibrosis, the 8-week-treatment with SIS3 in established db/db mice from 8 to 16 weeks significantly inhibited renal inflammation by suppressing F4/80+ macrophage infiltration and a marked upregulation of MCP-1, IL-1β, and TNF-α both locally and systematically." (PMID 38164169, 2024). "In unilateral UUO and folic acid renal fibrosis models, retinoic acid-inducible gene-I (RIG-I) functions as a promoter of NF-κB (nuclear factor-kappa B) signaling, leading to the activation of NF-κB signaling and facilitating the production and secretion of IL-1β and IL-6 in PTECs." (PMID 38260142, 2023). "In mesangial cells, C/EBPδ levels are upregulated by various factors, including IL-1β, LPS, TNF-α, and PDGF, and can mediate their trans-differentiation into myofibroblasts by directly upregulating α-SMA expression, thereby promoting the progression of renal fibrosis." (PMID 36299447, 2022). "Thus, Siglec-F+ neutrophils may contribute to renal fibrosis by 2 mechanisms, namely, by activating fibroblasts via their profibrotic cytokines (TGF-β1, TNF-α, and IL-1β) and by directly secreting COL1A1." (PMID 35482420, 2022). "Arid2-IR shares a similar mechanism with Ptprd-IR that overexpression of Arid2-IR may promote TGF-β1-, IL-1β-induced NF-κB-driven inflammation without affecting TGF-β/Smad3-mediated renal fibrosis." (PMID 34054586, 2021).